RN7SL581P (RNA, 7SL, cytoplasmic 581, pseudogene)
Gene: Miscellaneous RNA gene on chromosome X (70,222,006 to 70,222,314, reverse strand). Ensembl gene ENSG00000242657.
Homologues: Orthologues: chimpanzee Metazoa_SRP (98% identical), macaque Metazoa_SRP (92% identical). Paralogues in human: RN7SL1 (81% identical), RN7SL2 (80% identical), RN7SL3 (79% identical), RN7SL220P (78% identical), RN7SL126P (78% identical), RN7SL566P (78% identical), RN7SL448P (77% identical), RN7SL478P (77% identical), RN7SL218P (77% identical), RN7SL411P (77% identical), RN7SL127P (77% identical), RN7SL480P (77% identical), and 703 more.